SREBF2-AS1 (SREBF2 antisense RNA 1)
Synonyms: RP5; 821D11.7
Gene: Long non-coding RNA gene on chromosome 22 (41,831,215 to 41,834,665, reverse strand). Ensembl gene ENSG00000184068.
Diseases named in the same sentence as SREBF2-AS1 in open-access papers:
SREBF2-AS1 is named in the same sentence as 16 diseases in open-access papers, as found by Europe PMC text mining. Sharing a sentence is not in itself a finding about the gene and the disease.
SREBF2-AS1 shares sentences with these, for which no sentence is quoted: cancer (4 papers); infection (3); asthma (1); atherosclerosis (1); breast carcinoma (1); cannabis dependence (1); cervical squamous cell carcinoma (1); COVID-19 (1); glioma (1); Insulin resistance (1); lung carcinoma (1); ovarian carcinoma (1); schizophrenia (1); thyroid (1); tumours (1); type 2 diabetes (1).